GPX4 (glutathione peroxidase 4)
Diseases named in the same sentence as GPX4 in open-access papers (continued):
Sharing a sentence is not in itself a finding about the gene and the disease.
glioma (continued). "RSL3 (a GPX4 inhibitor) inactivates GPX4 and induces glycolytic dysfunction in glioma cells with reduced ATP and pyruvate content as well as HKII, PFKP, and PKM2 protein levels, which in turn induces ferroptosis." (PMID 36937406, 2023). "In this study, we identified TRIM26 E3 ubiquitin ligase as a key regulator of GPX4 proteasomal degradation in glioma cells." (PMID 37872147, 2023). "The inhibition of this modification impairs GPX4 protein stability, leading to ferroptosis in glioma cells." (PMID 37872147, 2023). "It has been demonstrated that a number of molecules affect the expression of GPX4 in gliomas to regulate ferroptosis." (PMID 36937406, 2023). "Numerous small molecule inhibitors have been developed and investigated for their ability to inhibit GPX4 and induce ferroptosis in various cancer types, including glioma." (PMID 38020609, 2023). "The overexpression of JUN in the glioma cells significantly increased the luciferase activity of the wild-type sequences in the GPX4 promoter region." (PMID 37375197, 2023). "For example, the inhibition of GPX4 has been shown to induce ferroptosis in glioma cells and enhance the cytotoxicity of chemotherapeutic agents." (PMID 38020609, 2023). "Clinically, TRIM26 expression shows a direct correlation with GPX4 and PLK1 levels in glioma samples and is associated with poor outcome in patients with glioma." (PMID 37872147, 2023). "Taken together, our data suggest that the natural product T4O exerts its anti-cancer effects by inducing JUN/GPX4-dependent ferroptosis and inhibiting cell proliferation, and T4O will hope-fully serve as a prospective compound for glioma treatment." (PMID 37375197, 2023). "The glioma cells treated with T4O showed a significant reduction in the expression of the negative regulators of ferroptosis, GPX4, COX2, SLC40A1, and SLC7A11." (PMID 37375197, 2023). "RSL3 can trigger ferroptosis by directly inhibiting GPX4 activity and inhibit the growth of glioma cells." (PMID 36569297, 2022). "Current research focuses on how to reduce drug resistance in glioma chemotherapy and deepens the mechanism of classical ferroptosis-inducing pathways such as GPX4 in glioma." (PMID 36185243, 2022). "In order to determine if ferroptosis is affected by PF treatment, we examined the expressions of STAT3/p-STAT3, Nrf2, and GPX4 in PF-treated glioma U87 cells, and found out that all these factors are inhibited at the protein level in a dosage-dependent manner." (PMID 36618071, 2022). "Protein molecules such as GPX4 and System Xc- and ferroptosis-related ncRNAs have become important targets for glioma therapy." (PMID 36185243, 2022). "The chaperone HSPA5 is involved in ferroptosis and contributes to an iron‐dependent non‐apoptotic cell death that stabilizes GPx4 and indirectly attenuates lipid peroxidation in glioma cells; therefore, we excluded HSPA5 from further study." (PMID 35984750, 2022). "It was reported that the biomimetic nanoparticles (PIOC@CM NPs) increased the level of ROS, depleted GSH upon ultrasonic irradiation and attenuated the activity of GPX4 to kill glioma C6 cells by activating ferroptosis." (PMID 36358495, 2022). "In the meantime, GAS increased the expression of HO-1, Nrf2, and GPX4 protein in Rat Glioma Cell Line C6, which protected Rat Glioma Cell Line C6 from ferroptosis induced by H2O2." (PMID 35516438, 2022). "Some ferroptosis inducers, such as plumbagin, triggers ferroptosis by inducing GPX4 degradation via the lysosome pathway and inhibiting glioma growth." (PMID 36358495, 2022). "Above all, these findings provide some new drug treatment options for glioma and demonstrate that GPX4 degradation promotes ferroptosis in glioma." (PMID 36358495, 2022). "Whereas studies show that GPX4 expression was significantly increased in human glioma patients compared to brain tissue of healthy patients." (PMID 36091118, 2022). "Our results demonstrated that Sev-induced ferroptosis in glioma cells was in a GPX4-dependent pathway." (PMID 35372041, 2022).
glioma (continued). "Higher GPX4 expression was observed in human glioma cells (U251 and U87) compared to normal glial cells, suggesting that ferroptosis sensitivity is reduced in this type of tumor." (PMID 35805884, 2022). "The upregulation of HSPA5 increases the expression and activity of GPX4, GPX4 protects glioma cells from ferroptosis by neutralizing DHA induced lipid peroxidation." (PMID 35478955, 2022). "Recently, a study revealed that when GPX4 is knocked down or reacts with its inhibitors, ferroptosis is activated to induce the death of glioma cells by accumulating lipid peroxides to damage the cell membrane and organelle membrane." (PMID 36358495, 2022). "HSPA5 has the effect of up-regulating the GPX4, which results in protecting glioma cells from ferroptosis, indicating the activation of ATF4 strengthens the drug resistance of glioma." (PMID 35784729, 2022). "Fragile X-related protein-1 RNA binding protein (FXR1) in glioma cells can bind to GPX4 mRNA and up-regulate GPX4 expression." (PMID 36185243, 2022). "We further demonstrated that Sev treatment suppressed the expression of GPX4, while upregulating the expression of transferrin and ferritin and Beclin-1 in glioma cells in a dose-dependent manner." (PMID 35372041, 2022). "Depleting GSH and Cys or inhibiting system Xc– and GPX4 impeded the survival of glioma cells and increased their sensitivity to radiation-induced lipid peroxidation." (PMID 34211978, 2021). "Many studies have shown that the expression of ferroptosis-related genes (including GPX4, SLC7A11, and ACSL4) is associated with sensitivity to temozolomide in glioma cells." (PMID 35174170, 2021). "Upregulated ATF4 increases the expression of HSPA5 and activity of glutathione peroxidase 4 (GPX4), thus protecting glioma cells from ferroptosis." (PMID 34163322, 2021). "In general, the ACSL4/GPX4 pathway can inhibit the proliferation of glioma cells by activating ferroptosis, thus providing a new idea for the treatment of glioma." (PMID 34944434, 2021). "The siRNA-mediated silencing of ACSL4 promoted the proliferation in glioma cells via the decrease in ferroptosis through the enhancement of GPX4 expression." (PMID 32656078, 2020). "All these results suggest that ACSL4 inhibition directly affects the expression of GPx4, which finally promotes glioma cell proliferation by inhibiting ferroptosis." (PMID 32656078, 2020). "Treatments with 5 and 6 caused a significant decrease in mRNA expression of both GPx1 and GPx4 in all four glioma cell lines." (PMID 33134322, 2020). "We next restored GPX4 activity in glioma cells using an HA-tagged GPX4 expression vector in HSPA5-silenced glioma cells." (PMID 31519193, 2019). "miR-139-5p reduces HMGCR expression in glioma cells and downregulates GPX4 expression." (PMID 40399275, 2025). "The LDA results revealed a significantly increased expression of iron metabolism-related genes ferritin heavy chain 1 (FTH1), transferrin receptor (TFRC), and Acyl-CoA synthetase long-chain family member 4 (ACSL4), while GPX4 expression was decreased in the glioma samples compared to the controls." (PMID 41154694, 2025). "Metformin can mainly inhibit GPX4 protein expression in glioma cells, promote the expression of Long-chain acyl-CoA synthetase 4 (ACSL-4) protein, which leads to the increase of Reactive Oxygen Species(ROS) level, triggers ferroptosis, and inhibits glioma proliferation." (PMID 39944825, 2025). "Studies have shown that Salmonella infection may elevate ROS and glutathione levels, and that engineered Salmonella YB1 can reduce GPX4 expression in glioma cells, inducing ferroptosis." (PMID 40442779, 2025). "However, the role of GPX4’s independent ferroptosis regulatory mechanism in various states of glioma cells requires further investigation, which will be a primary focus of our future research." (PMID 40822852, 2025).
glioma (continued). "Moreover, this study is the first to establish a link between SOX10 overexpression in glioma cells and its involvement in ferroptosis signalling, specifically through the GPX4/ACSL4 axis in U87 cells." (PMID 40159622, 2025). "A convey revealing the relationship between ferroptosis-related genes (FRGs) and gliomas indicated that interferon regulatory factor 2 (IRF2) was positively associated with glioma grade and contributed to gliomas, potentially by maintaining low ACSL4 level and high xCT/GPX4 level." (PMID 39309434, 2024). "Furthermore, HSPA5 has been reported to maintain the stability of GPx4, a critical enzyme involved in lipid peroxidation and protection against ferroptosis, in glioma cells." (PMID 38494858, 2024). "In glioma, inhibition of GPX4 can accelerate the occurrence of ferroptosis." (PMID 39857625, 2024). "Inspired by the boron neutron capture therapy, a new form of cancer therapy that is currently being researched using boron-containing agents and ionizing radiation, borax (sodium borate) induced ferroptosis in glioma cells in vitro by inhibiting the HSPA5/NRF2/GPX4/GSH signaling pathways." (PMID 39062119, 2024). "The expression of GPX4 was progressively enhanced with increasing WHO glioma grading." (PMID 36910646, 2023). "The five glioma cell lines assayed had baseline sensitivity to ferroptosis by the GPX4 inhibitor RSL3, confirmed by live-cell confocal microscopy showing RSL3 mediated induction of lipid peroxidation as evidenced by green fluorescence shift in the Bodipy-C11 dye following addition of RSL3." (PMID 36864031, 2023). "Compound 110 decreased SLC7A11, cysteine, and GSH levels enhanced the expression of NOX4, which reduces oxygen to superoxide radical anions, rose the labile iron pool, and surprisingly upregulated GPX4 in diverse rat and human glioma cell lines (C6, SHG‐44, U87, U251) and/or grafted tumors in mice." (PMID 36658724, 2023). "GPX4 is also involved in the proliferation, migration, and apoptosis of glioma cells." (PMID 36618071, 2022). "ASCL4 was considered as a sensitive monitor as well as an important contributor of ferroptosis and eliminated the inhibition of GPX4 on ferroptosis in osteosarcoma cells, and overexpression of ACSL4 in glioma significantly reduced GPX4 level and contributes to ferroptosis." (PMID 36407113, 2022). "Furthermore, our xenograft data demonstrated that PF can suppress glioma tumor growth by activating NEDD4L/STAT3/Nrf2/GPX4 signal axis which eventually triggers ferroptosis." (PMID 36618071, 2022). "Moreover, ATF4 suppression obviously reversed the regulatory role of Sev on protein levels of GPX4, transferrin, and ferritin in glioma cells." (PMID 35372041, 2022). "Nrf2 can also inhibit ferroptosis by up-regulating GPX4 expression in glioma cells." (PMID 36185243, 2022). "Specifically, DHA could promote the development of ACSL4 and xCT, but significantly downregulated GPX4 levels, initiating the death of glioma cells by maintaining ferroptosis." (PMID 36358495, 2022). "Iron oxide nanoparticles loaded with paclitaxel (IONP@PTX) not only inhibited the migration and invasion of glioma cells by enhancing ions, ROS and lipid peroxidation, but also promoted the autophagy-dependent ferroptosis pathway by decreasing the levels of GPX4 in vitro." (PMID 36358495, 2022). "Since six signature genes of the 19 ferroptosis-related genes were involved in the GPX4 regulation, GPX4 and its role in ferroptosis might play a crucial role regarding survival of glioma patients." (PMID 35530303, 2022).
glioma (continued). "Taken together, this study demonstrates that PF can function as an antitumor agent for glioma treatment by targeting NEDD4L-dependent STAT3 ubiquitination as well as by regulating the Nrf2/GPX4 signaling axis, which might trigger ferroptosis." (PMID 36618071, 2022). "It was reported that knockdown of GPX4 induced apoptosis of glioma cells." (PMID 33472669, 2021). "The treatment of glioma cells with the GPX4 inhibitor RSL3 can enhance the ferroptosis of cells." (PMID 32656078, 2020). "All these studies suggest that GPX4 may play an important role in the resistance of tumor cells by regulating ferroptosis, including glioma TMZ resistance, but the regulatory mechanisms need further study." (PMID 32656078, 2020). "Silencing HSPA5 by siRNAs suppressed GPX4 expression in glioma cells." (PMID 31519193, 2019). "This shows that GPX4 could be employed as a therapeutic target for glioma." (PMID 40969276, 2025). "It is significant to note that glioma cells may orchestrate GPX4 to favor their malignancies." (PMID 39309434, 2024). "However, researchers have revealed that activated ER stress by DHA might in turn enhance the expression and activity of GPX4, which neutralizes the glioma-killing effect of DHA124." (PMID 39309434, 2024). "Therefore, the use of GPX4 inhibitors can effectively induce ferroptosis in glioma cells." (PMID 39857625, 2024). "In addition, SLC1A5 knockdown could significantly inhibit glioma cell proliferation and invasion, and reduce the sensitivity of ferroptosis via the GPX4-dependent pathway." (PMID 36566214, 2022). "Whether GPX4-induced chronic inflammation engaged in glioma progression or outcome." (PMID 35832539, 2022). "However, GPX4 is an essential gene in mammals, and whether drugs that inhibit GPX4 to treat tumors will bring unbearable side effects to glioma patients remains to be further studied." (PMID 36185243, 2022). "In addition, our data demonstrated that forced expression of NEDD4L inhibits glioma cell growth probably by inducing ferroptosis, characterized by intracellular ROS accumulation and suppressed expression of the key factors in ferroptosis such as Nrf2 and GPX4." (PMID 36618071, 2022). "Therefore, the reduced expression of Nrf2 and GPX4 driven by oeNEDD4L might contribute to the suppressed glioma cell growth by multiple means." (PMID 36618071, 2022). "Currently, researchers have demonstrated that lonizing radiation could consume GSH, inhibit GPX4 activity, and induce ferroptosis, and they denote that ferroptosis should be essential for glioma treatment because radiotherapy is an important part of Stupp strategy." (PMID 35832539, 2022). "Additionally, in both in vivo and in vitro models of glioma, the mechanism by which dihydroartemisinin exerts anticancer effects on glioma cells was found to be dependent on promoting ferroptosis via the PERK–ATF4–heat shock protein family A member 5 (HSPA5)–GPX4 pathway." (PMID 35082783, 2021). "GRP78 plays a critical role in preventing glutathione peroxidase 4 (GPX4) degradation, consequently augmenting the resilience of pancreatic cancer and glioma cells against ferroptosis." (PMID 40362432, 2025). "We demonstrate that boric acid modulates the SOX10/GPX4/ACSL4 axis, elucidating the involvement of SOX10 signalling in ferroptosis within glioma cells." (PMID 40159622, 2025). "We also analyzed glioma cell data from the Cancer Cell Line Encyclopedia (CCLE) to verify if Notch signaling alone was predictive of response to GPX4 inhibitors using in vitro models." (PMID 39192032, 2024). "Previous studies have shown that the synthetic small molecule GPX4 inhibitor RSL3 can effectively inhibit the development of colorectal cancer, breast cancer, and glioma." (PMID 39368999, 2024). "Our study shows that erastin treatment significantly downregulated the expression of GPX4 and SLC7A11, confirming the occurrence of ferroptosis in glioma cells." (PMID 39857625, 2024).
glioma (continued). "Dihydroisotanshinone I suppresses proliferation and induces the ferroptosis of glioma cells by upregulating the ferroptosis-inducing ACSL4 gene and downregulating the ferroptosis-inhibiting GPX4 gene." (PMID 38892270, 2024). "The study also highlighted the inhibitory effect of borax‐induced ferroptosis on cell proliferation in glioma cells, achieved through the modulation of the HSPA5/NRF2/GPx4/GSH regulatory pathways." (PMID 38494858, 2024). "Conversely, in glioma and TNBC, GPX4 knockout in B cells suppresses immune responses through lipid peroxidation and ferroptosis." (PMID 39867656, 2024). "In conclusion, our findings suggest that C5aR1 inhibits ferroptosis in GBM cells and promotes MettL3-dependent GPX4 expression through ERK1/2, thereby promoting glioma progression." (PMID 39368999, 2024). "For instance, TRIM26 is overexpressed in glioma and suppresses ferroptosis via the degradation of GPX4, while RNF139 inhibits glioma cell growth through PI3K/AKT signaling in a ubiquitination-dependent manner." (PMID 39075053, 2024). "Since ferroptosis-related genes including xCT, GPX4 and FTH1 present as targets of Nrf2, many treatments seek to disturb ferroptosis by manipulating Nrf2 in gliomas." (PMID 39309434, 2024). "In cancer cell studies, dihydroartemisinin inhibits proliferation and migration and triggers the ferroptosis of glioma cells by upregulating the ferroptosis-inducing HMOX1 gene and downregulating the ferroptosis-inhibiting GPX4 gene." (PMID 38892270, 2024). "Herein we show that cysteine and methionine deprivation (CMD) can synergize with the GPX4 inhibitor RSL3 to increase ferroptotic cell death and lipid peroxidation in both murine and human glioma cell lines and in ex vivo organotypic slice cultures." (PMID 36864031, 2023). "PLK1 inhibition led to ferroptosis in glioma cells by dephosphorylating TRIM26, further resulting in GPX4 degradation." (PMID 37872147, 2023). "ACSL4 overexpression was found to decrease GPX4 overexpression and increase ferroptosis marker levels, such as 5-hydroxyeicosatetraene (5-HETE), 12-HETE and 15-HETE, in glioma cells." (PMID 36937406, 2023). "In multiple tumors including glioma, FIN56 has been shown to significantly decrease GPX4 expression, increase intracellular peroxide levels, induce cell ferroptosis, and effectively inhibit tumor cell proliferation." (PMID 38020609, 2023). "After further study, we found that SLC1A5 is a suppressor of ferroptosis in glioma, and knockdown of SLC1A5 can downregulate the expression of GPX4." (PMID 37566748, 2023). "It inhibits the proliferation of glioma cells in vitro and in vivo by promoting GSH depletion and low GPX4 expression to increase ferroptosis." (PMID 36358495, 2022). "Dihydrotanshinone I (DHI), which boosted ferroptosis by decreasing the expression level of GPX4 and increasing that of ACSL4, inhibited the growth and proliferation of glioma cells." (PMID 36358495, 2022). "After knockdown of circCDK14 in glioma cells, protein levels of SLC7A11 and GPX4 decreased significantly and Fp became more sensitivity." (PMID 35002529, 2022). "For instance, capsaicin, as a potential anticancer ferroptosis inducer, suppresses the proliferative effects of glioma cells by increasing ACSL4 levels and decreasing GPX4 levels to induce ferroptosis." (PMID 36358495, 2022). "After treatment of human glioma cells with dihydrotanshinone I, GPX4 expression decreased while ACSL4 expression increased, inducing ferroptosis in human glioma cells." (PMID 36091118, 2022). "Their study showed that the GPX4 expression level significantly increased, whereas 12-HETE and 15-HETE expression levels decreased in human glioma tissues and cells." (PMID 34944434, 2021). "Therefore, ACSL4 may also regulate TMZ resistance in gliomas by affecting the GPX4 expression." (PMID 32656078, 2020).